DUXAP8 (double homeobox A pseudogene 8)
Diseases named in the same sentence as DUXAP8 in open-access papers (continued):
Sharing a sentence is not in itself a finding about the gene and the disease.
tumor (continued). "The expression of LncRNA DUXAP8 in tumor tissues was significantly higher than that of the normal tissue (P<0.001)." (PMID 33817152, 2019). "Conversely, LncRNA DUXAP8 knockout significantly suppressed cell proliferation, weakened invasion and inhibited tumor growth." (PMID 33817152, 2019). "LncRNA DUXAP8 overexpression induced tumor growth, but LncRNA DUXAP8 knockout inhibited tumor growth." (PMID 33817152, 2019). "Construction of LncRNA DUXAP8 overexpression and LncRNA DUXAP8 knockout in A549 cell lines was further performed and subsequently injected into nude mice to build an in vivo tumor xenograft model." (PMID 33817152, 2019). "The tumor grew slowly when LncRNA DUXAP8 was knocked out; in contrast, LncRNA DUXAP8 overexpression rapidly promoted tumor growth (considering tumor volumes and tumor weight; compared with EV group, P < 0.001)." (PMID 33817152, 2019). "Tumor xenograft was further constructed based on A549 cells with LncRNA DUXAP8 overexpression and knockout." (PMID 33817152, 2019). "Meanwhile, the larger the tumor diameter, the higher the LncRNA DUXAP8 expression, with the expression in tumor diameter ≥ 3cm significantly higher than that in tumor diameter < 3 cm (P<0.001)." (PMID 33817152, 2019). "Conversely, LncRNA DUXAP8 knockout significantly suppressed A549 cells’ proliferation, weakened invasion and inhibited tumor growth." (PMID 33817152, 2019). "QRT-PCR assays showed lower DUXAP8 levels in the tumor tissues derived from sh-DUXAP8-transfected cells." (PMID 30367681, 2018). "sh-DUXAP8 markedly suppressed the growth of the xenografts with a significantly lower tumor volume and weight versus the controls." (PMID 30367681, 2018). "Patients with high and low DUXAP8 expression differed significantly in tumor size (P = 0.033) and TNM stages (P = 0.0034)." (PMID 30367681, 2018). "qRT-PCR analysis also revealed that the level of DUXAP8 expression in tumor tissues formed from sh-DUXAP8 cells was lower than in tumors formed in the control group." (PMID 28881724, 2017). "We further discovered that DUXAP8 upregulation was also correlated with larger tumor size, advanced clinical stage, lymphatic metastasis, and poor prognosis of patients with GC." (PMID 28881724, 2017). "DUXAP8 can enhance SOSS1 and activate downstream proliferative signaling by sponging miR-20b-5p, which is ultimately associated with a poorer prognosis and a higher tumor grade." (PMID 41154428, 2025). "Furthermore, the evaluation of CRC patients defined the upregulation of DUXAP8 in tumor samples compared to normal tissues." (PMID 40556338, 2025). "Depriving DUXAP8 can suppress tumor growth and improve sorafenib efficacy in clinical HCC patients." (PMID 37337470, 2023). "The results above confirmed that DUXAP8 may contribute to sorafenib resistance and silencing DUXAP8 may enhance tumor cell ferroptosis." (PMID 37337470, 2023). "Furthermore, DUXAP8 overexpression has been detected in pancreatic cancer cells, and its suppression leads to reduced cell growth and inhibition of tumor growth, accompanied by increased expression of multiple genes involved in tumor suppression." (PMID 37627052, 2023). "Recently, increasing studies are investigating the DUXAP8 role in tumor." (PMID 35287542, 2022). "Double homeobox A pseudogene 8 (DUXAP8) is a known tumor promoter in several malignancies." (PMID 35287542, 2022). "Based on our analysis, DUXAP8 knockdown remarkably decreased tumor volume, relative to controls." (PMID 35287542, 2022). "In addition, we employed data mining to investigate the prognostic value of DUXAP8 in a range of tumor types to further validate our results." (PMID 36046244, 2022). "DUXAP8 expression is substantially increased in LUAD tumor tissues." (PMID 34631702, 2021). "In pancreatic cancer, DUXAP8 promotes tumor growth through epigenetic silencing of CDKN1A and KLF2." (PMID 34957112, 2021). "Besides, enhanced RCN2 expression restored the tumor growth in vivo that was inhibited by DUXAP8 repression." (PMID 34774078, 2021).
tumor (continued). "Various tumor stages and tumor sizes had different expression levels of LncRNA DUXAP8." (PMID 33817152, 2019). "Moreover, tumor growth in the sh-DUXAP8 group was significantly slower than that in the control group." (PMID 28881724, 2017). "Interestingly, we found some novel lncRNAs that associated with increased metastatic activity in metastatic RCC tumor biopsies, such as DUXAP8." (PMID 29152119, 2017). "Taken together, these results suggested that DUXAP8 might play a pro-tumor role in PTC development." (PMID 33522355, 2021). "Emerging literature supports that overexpressed lncRNA DUXAP8 might function as a sponge in cancer tissues, targeting tumor suppressive microRNAs, thereby facilitating target oncogene signaling pathway activity and promoting tumor development and progression." (PMID 34631702, 2021). "LncRNA DUXAP8 could be a potential marker in tumor cell invasion of NSCLC." (PMID 33817152, 2019). "Here, we engaged the pseudogene DUXAP8 into a feedback loop affecting the HCC indicator Piezo1 and concerning the HCC tumor microenvironment (TME)." (PMID 42278405, 2026). "The knockdown of DUXAP8 sensitized MDA-MB-231 cells to irradiation in vivo, as evidenced by the reduced tumor volume and weight in DUXAP8 knockdown group." (PMID 36329030, 2022). "In the present study, both DUXAP8 and MIR4435-2HG were positively correlated with M2 macrophages, which have a role in promoting tumor development, angiogenesis, and tumor cell metastasis and help tumor cells evade immune recognition." (PMID 35201491, 2021). "For the KEGG pathway, CAHM, DUXAP8, MKLN1-AS, and RHPN1-AS1 were all enriched in these tumor proliferation-related pathways such as Spliceosome, Cell cycle, DNA replication, and RNA transport, suggesting their important role in the tumorigenesis." (PMID 34917132, 2021). "In colon cancer tissues, DUXAP8, RP11-54H7.4, and RP11-138J23.1 show elevated expression in advanced tumor stages." (PMID 34947885, 2021). "In summary, the MIR4435-2HG/hsa-miR-1-3p/MMP9/hsa-miR-29-3p/DUXAP8 ceRNA network axis was constructed by using bioinformatical tools, and it might be closely associated with the development of HCC, associated with a poor prognosis in HCC patients, and associated with tumor immune cell infiltration." (PMID 35201491, 2021). "A nomogram was constructed using tumor stage, HBV infection status, radical resection status, and expressions of DUXAP8 and RNF2." (PMID 32922554, 2020). "Noticeably, high DUXAP8 expression in GC was significantly correlated with advanced TNM stage (P=0.001), lymph node metastasis (P=0.007), and tumor size (P=0.002)." (PMID 28881724, 2017). "Correlation analysis with clinicopathological parameters showed that high levels of DUXAP8 correlated with the TNM stage of cancer, tumor size, microvascular invasion, and distant metastasis, and that HCC patients with high DUXAP8 expression tended to have a poorer prognosis." (PMID 34957112, 2021). "However, only DUXAP8 and RNF2 showed prognostic value in multivariate analysis, after adjustment for tumor stage, HBV infection, and radical resection factors (adjusted p=0.014 and 0.008, respectively)." (PMID 32922554, 2020). "Consistenly, the results showed that the expression of DUXAP8 in tumor tissues was significantly higher than that in nontumor tissues." (PMID 32022476, 2020). "Low expressions of DUXAP8 and RNF2, tumor stage I, without HBV infection and radical resection, were correlated with low-risk scores, and hence better patient survival." (PMID 32922554, 2020). "In this study, qRT-PCR showed that LncRNA DUXAP8 were significantly up-regulated in NSCLC tissues compared with non-tumor lung tissues, especially in stage III / IV and tumor diameter ≥ 3 cm." (PMID 33817152, 2019).
cancer (29 papers, 2017 to 2025). A tumor composed of atypical neoplastic, often pleomorphic cells that invade other tissues. "DUXAP8 has been implicated in various cancer types and contributes to tumorigenesis through different mechanisms." (PMID 37627052, 2023). "Its expression has been associated with worse clinical features, and knockdown of DUXAP8 reduces cancer cell growth and survival, leading to increased expression of EGR1 and RHOB transcripts." (PMID 37627052, 2023). "Double homeobox A pseudogene 8 (DUXAP8), as a novel, long noncoding RNA, is associated with a number of cancers, including liver, colorectal, bladder, oral, ovarian, lung, and pancreatic tumors." (PMID 36313616, 2022). "Pseudogene-derived long noncoding RNA(lncRNA) is currently thought to have an important role in the development of human cancers, and a previous experiment in nude mice, as well as NB cell lines, confirmed that the pseudogene DUXAP8 is associated with the progression and poor prognosis of NB." (PMID 37790931, 2023). "In addition, univariate and multivariate Cox regression analyses revealed that DUXAP8 expression level and cancer status were significantly associated with prognosis of HCC patients." (PMID 37337470, 2023). "Although many studies found that lncRNA DUXAP8 serves as an important prognostic factor for patients with a variety of tumors, the underlying systems of how the lncRNA DUXAP8 impacts cancer are still unknown." (PMID 36046244, 2022). "Expression of the lncRNA DUXAP8 was significantly higher in HCC than in para-cancer normal tissues, potentially because of METTL3 binding to the m6A site on DUXAP8." (PMID 41298358, 2025). "For instance, dual homeoboxes A pseudogene 8 (DUXAP8) was closely related to poor overall survival in several cancers, suggesting its ability to serve as a prognostic biomarker and potential therapeutic target for cancers." (PMID 39090722, 2024). "DUXAP8 is a biomarker and therapeutic target of various cancers that is upregulated in GC, promotes cell proliferation and migration, and then accelerates the development of GC32, and this study verified the upregulation of DUXAP8 in GC." (PMID 37258567, 2023). "DUXAP8 is a pseudogene-derived lncRNA that is upregulated in various human cancers and can be used as a biomarker for pan-cancer diagnosis and/or prognosis." (PMID 37349838, 2023). "To investigate the biological function and KEGG pathway of DUXAP8 expression in pan-cancers, we conducted GESA." (PMID 36046244, 2022). "A correlation analysis has been performed to explore between DUXAP8 and the poor OS in patients diagnosed with cancer." (PMID 36046244, 2022). "DUXAP8-related molecular targets, proteins, pathways, and noncoding RNA (microRNAs and circRNAs) were methodically described in this meta-analysis to provide a reference for mechanistic exploration into the carcinogenesis function of DUXAP8 in various cancers." (PMID 36046244, 2022). "For instance, pseudogenes DUXAP8, MST O 2P and MYLKP1 involved in supporting CRC progression and enhance cancer risk." (PMID 36866106, 2022). "We first used GEPIA to investigate DUXAP8 expression in pan-cancer from the TCGA and GTEx databases." (PMID 36046244, 2022). "There was a pooled HR = 1.63 between DUXAP8 and the OS (95% CI, 1.49–1.77, p < 0.001), revealing significantly worse OS in the cancer patients with high expression of DUXAP8." (PMID 36046244, 2022). "To further explore the prognostic role of DUXAP8 expression levels in cancers, we used the GEPIA2 survival analysis module and found that high DUXAP8 mRNA expression correlated with poor overall survival in seven cancers." (PMID 34631702, 2021). "DUXAP8 expression is positively related to the cancer grade, and it influences miR-409-3p expression in a sponging-dependent manner and promotes HK2 as well as LDHA expression." (PMID 34947885, 2021).
cancer (continued). "The potential regulatory effects of DUXAP8 on the expression of the cancer stem cell marker, CD133, and stem cell-related genes, including OCT4, NANOG, and Sox2 were then investigated." (PMID 34957112, 2021). "We identified that DUXAP8 was remarkably increased in cancer samples compared with their corresponding normal samples." (PMID 33269379, 2021). "In this review, we comprehensively explore DUXAP8 expression and prognosis across cancer types, and systematically summarize current evidence concerning the functions and molecular mechanisms of DUXAP8 in tumorigenesis and progression." (PMID 34631702, 2021). "Previous experiments reported that DUXAP8 was overexpressed in cancers and that its aberrant upregulation promoted cancer cell growth, which is consistent with our results." (PMID 34235076, 2021). "It was confirmed by RT–qPCR that DUXAP8 expression in HCC tissues was significantly higher than that of normal tissues adjacent to cancer, and the same results were obtained after expanding the sample size." (PMID 34957112, 2021). "Long non-coding RNA (lncRNA) DUXAP8 has been reported to participate in the proliferation, migration, and invasion of several cancer types." (PMID 33522355, 2021). "To characterize mRNA expression levels of DUXAP8 in 33 different cancers, we developed gene expression profiling interactive analysis 2 (GEPIA2) and determined that DUXAP8 displays markedly different expression levels among cancers." (PMID 34631702, 2021). "Long noncoding RNAs (lncRNAs) play a critical role in the pathogenesis of human cancers, while the function of double homeobox A pseudogene 8 (DUXAP8) in LUAD remains to be fully inquired." (PMID 33269379, 2021). "Increasing evidences have demonstrated that DUXAP8 plays a regulatory role in many cancers, including NSCLC, gastric cancer etc." (PMID 33269379, 2021). "Double Homeobox A Pseudogene 8 is markedly upregulated in various cancer tissues, which plays an important role in cancer initiation and progression." (PMID 34631702, 2021). "The Cancer Cell Line Encyclopedia (CCLE) database revealed that DUXAP8 in A549 and H1299 cells was significantly higher than in IMR-90 cells." (PMID 34235076, 2021). "In summary, we unraveled that silencing DUXAP8 expression suppresses cell proliferation and enhanced apoptosis by targeting miR-26b-5p, which serves as a cancer facilitator in LUAD." (PMID 33269379, 2021). "Several studies have revealed that DUXAP8 participates in the development of various cancers." (PMID 37349838, 2023). "Double‐homeobox A pseudogene 8 (DUXAP8) is a lncRNA that acts as regulatory factor in many cancers." (PMID 34907642, 2022). "LncRNA DUXAP8 is previously reported as an oncogene in several cancers." (PMID 35311115, 2022). "In addition, elevated DUXAP8 expression was closely related to poor OS in several cancers in the TCGA database." (PMID 36046244, 2022). "Thus, we performed this meta-analysis for the first time to explore the clinical prognostic role and functions of DUXAP8 in human cancers." (PMID 36046244, 2022). "DUXAP8 exerts an essential role in tumorigenesis, proliferation, migration, invasion, and inhibition of apoptosis, which means that DUXAP8 acts as an oncogene in the occurrence and development of various malignant tumors." (PMID 36046244, 2022). "This study revealed that DUXAP8 might serve as a prognostic biomarker and potential therapeutic target for cancer." (PMID 36046244, 2022). "To assess DUXAP8’s ability to predict pan-cancer, we evaluated multiple datasets." (PMID 36046244, 2022). "The research suggested that DUXAP8 expression may have an effect on cancer patients’ response to immune checkpoint therapy, which will benefit the further understanding of immunotherapy’s molecular mechanism in cancer treatment." (PMID 36046244, 2022). "The clinical information of double homeobox A pseudogene 8 (DUXAP8) in pan-cancers." (PMID 34631702, 2021). "Until now, DUXAP8 is highly expressed in various malignant tumors." (PMID 34957112, 2021).
cancer (continued). "Recently, DUXAP8 has been shown to be highly expressed in various malignant tumors." (PMID 34957112, 2021). "In addition, compared with 16HBE cells, DUXAP8 expression levels was significantly up-regulated in cancer cells (A549, H1299, H1975)." (PMID 33269379, 2021). "DUXAP8 was recently identified as a pan-cancer gene using meta-analysis and TCGA pan-cancer data." (PMID 33318305, 2020). "Bioinformatics analysis showed that DUXAP8 was involved in regulating cancer proliferation in HCC." (PMID 32849765, 2020). "What's more upregulation of PDK2 is associated with metabolic reprogramming and chemoresistance of cancer cells, so it is also worth studying whether DUXAP8 can modulate these phenotypes of HCC cells." (PMID 32022476, 2020). "In addition, other downstream miRNAs of DUXAP8 needs to be screened and validated, which can better clarify the mechanism by which DUXAP8 promotes cancer progression." (PMID 32022476, 2020). "In triple negative breast cancer, DUXAP8 is activated by the YY1 transcription factor, and it promotes cellular proliferation of cancer cells via upregulation of SAPCD216." (PMID 35287542, 2022). "This study found that the expression of DUXAP8 is significantly correlated with TMB in seven cancer types and MSI in seven cancer types." (PMID 36046244, 2022). "This study included an in-depth analysis of DUXAP8 expression levels, as well as the relationship with TMB, MSI, MMR, DNMTs, and immune checkpoint biomarkers in 33 cancer types." (PMID 36046244, 2022). "Among these genes, BUB1 was reported as a key regulator in multiple cancer progression, including HCC, and was selected as the downstream target of DUXAP8." (PMID 32849765, 2020). "Two pseudogenes DUXAP8 and DUXAP9 were significantly upregulated in cancer samples compared with normal samples." (PMID 31409759, 2019). "Expression of DUXAP8, DUXAP9, COL1A1 and COL1A2 were significantly increased in cancer samples compared to normal controls while miR-29c-3p expression was decreased." (PMID 31409759, 2019). "Therefore, it is insightful to assess the role of DUXAP8, miR‐485‐5p and FOXO1 in the development of other types of cancer." (PMID 34907642, 2022). "qPCR showed that DUXAP8, DUXAP9, COL1A1 and COL1A2 were significantly upregulated in renal cell carcinoma cancer samples compared with normal controls whereas miR-29c-3p expression in cancer tissues was decreased." (PMID 31409759, 2019). "MiR-584-5p has been shown to be involved in regulating multiple malignant tumors, and it was found that in HCC tissues, DUXAP8 showed a significant negative correlation with miR-584-5p expression." (PMID 34957112, 2021).
metabolic disorder (1 paper, 2023). "Here, we report that DUXAP8 induced cystine depletion, substantial enhancement of lipid peroxidation, and ferrous ion metabolic disorder in HCC cell lines, while SLC7A11 could reverse the effects of DUXAP8 on ferroptosis in HCC." (PMID 37337470, 2023).
DUXAP8 also shares sentences with these, for which no sentence is quoted: cervical cancer (2 papers); B-cell acute lymphoblastic leukemia (1); breast invasive carcinoma (1); colon adenocarcinoma (1); esophageal squamous cell carcinoma (1); gastric adenocarcinoma (1); leukemia (1); Pan (1); renal carcinoma (1).